INS (insulin)
Diseases named in the same sentence as INS in open-access papers (continued):
Sharing a sentence is not in itself a finding about the gene and the disease.
Obesity (continued). "Association of aldosterone with obesity, lipid levels, and IR had been confirmed by studies as adipokines and insulin stimulates aldosterone production, which in turn causes fluid retention, endothelial cell dysfunction, atherosclerosis, and HTN." (PMID 22957211, 2012). "The roles of B1R in adipocytes have systemic contributions to metabolic homeostasis, since exclusive expression of these receptors in fat cells is able to control whole body insulin sensitivity and predisposition to obesity." (PMID 23024762, 2012). "To examine the association of the Rgs5 gene and inflammation with obesity, we investigated the gene expression of inflammatory mediators in major insulin-responsive tissues of mice fed an HF." (PMID 22272317, 2012). "Omentin-1 enhances insulin action; is inversely related to obesity; is increased after weight loss; and is downregulated by insulin and glucose." (PMID 22952622, 2012). "Genetic SCD-1 deficiency in mice is linked to resistance to obesity and improved insulin sensitivity, partly mediated via suppression of the negative regulator of insulin signaling, protein tyrosine phosphatase-1B (PTP-1B)." (PMID 21543215, 2012). "For example, obesity andtype 2 diabetes have been linked to ER stress-induced failure of insulin-producingpancreatic beta cells, and current research efforts are aimed at developing drugs thatameliorate cellular stress and thereby protect beta cell function." (PMID 24278747, 2012). "Insulin level has the second largest number, which fits well with the fact that impaired compensatory insulin secretion under obesity is also a causal factor in T2D." (PMID 23028558, 2012). "It is a proinflammatory cytokine that exerts numerous effects in adipose tissue including lipid metabolism and insulin signaling whose circulating levels are increased with obesity and decreased with weight loss." (PMID 22523672, 2012). "The lack of correlation with BMI is probably due to the relatively limited range of BMI in this cohort since BMI is well known to be associated with insulin sensitivity in large population samples with different degree of obesity." (PMID 22992414, 2012). "Noteworthy is that leptin deficient mice exhibit hyperplasia partly due to increased concentrations of other obesity-associated endocrine and mitogenic factors such as insulin and IL-6." (PMID 23216800, 2012). "Our studies confirmed earlier reports showing that mice lacking CD36 were significantly protected against HFD-induced obesity associated with increased plasma insulin and glucose levels and reduced glucose tolerance." (PMID 22615812, 2012). "SCD1-deficient mice have shown resistance to diet-induced obesity, increased insulin sensitivity, reduced hepatic lipid accumulation, and/or even increased energy expenditure." (PMID 22363472, 2012). "The effect of exogenous leptin on insulin's actions and metabolic outputs has been studied mainly in leptin-deficient patients, as well as in models of experimental diabetes or obesity." (PMID 23056516, 2012). "Low serum amylase is likely to be associated with obesity and metabolic abnormalities, which are often accompanied by impaired insulin action." (PMID 22748134, 2012). "In the vasculature, insulin stimulates NO release through Akt, and decreased insulin-stimulated NO release is associated with obesity." (PMID 22934083, 2012). "IL-6 is markedly produced during the post-exercise period when insulin action is enhanced, but IL-6 is also associated with obesity and reduced insulin action." (PMID 23136874, 2012). "This study is the first to clarify the role of RGS5 in obesity-associated metabolic dysfunction and insulin sensitivity." (PMID 22272317, 2012). "The pathophysiologic hallmark of T2DM is obesity-related loss of insulin potency (peripheral resistance), which leads to an increased insulin-demand that ultimately exceeds the insulin-producing capacity of islet β-cells." (PMID 22962620, 2012).
Obesity (continued). "On the other hand, IR is strongly associated with obesity and is believed to precede the impairment in insulin secretion." (PMID 23283045, 2012). "Hepatic steatosis is associated with obesity and obesity is associated with a reduced insulin clearance." (PMID 22829877, 2012). "Since these diseases have origins in pediatrics and are associated with obesity, this study was designed to determine if obesity has different effects on endothelial function, insulin sensitivity, and secretion in African-American and Caucasian adolescents." (PMID 24533206, 2012). "Inhibiting autophagy in adipose tissue leads white adipocyte to acquire features of brown adipocyte, therefore exerting an anti-obesity effect and improving obesity associated insulin sensitivity." (PMID 23039759, 2012). "The population had a wide range of age and obesity, markers of glucose metabolism (fasting glucose, 2-hour glucose and insulin sensitivity) as well as cardiovascular risk factors (Framingham risk score, total cholesterol and HDL cholesterol)." (PMID 22720085, 2012). "Previous studies have demonstrated the relationship between obesity, hyperleptinemia and reduced insulin sensitivity and the beneficial effect of weight loss on insulin action." (PMID 23056516, 2012). "It is interesting to note that the relationship between apelin and insulin or TNFα during obesity and obesity-associated disorders was still maintained at the end of the aerobic exercise but was dependent on the magnitude of insulin sensitivity." (PMID 23653851, 2012). "The current review discusses the role of insulin and insulin-like growth factor-1/FoxO-mediated transcription for the pathogenesis of obesity-associated dementia from model organisms to humans." (PMID 22654904, 2012). "Dysfunctional secretion of adipokines and free fatty acids contributes to the development of an inflammatory state and has a causal role for the development of the insulin-resistant state of obesity." (PMID 22235202, 2012). "Meanwhile, increased levels of endogenous hormones associated with overweight and obesity, such as sex steroids, insulin, insulin-like growth factor I, and leptin, have been described as potential mechanisms linking obesity to prostate cancer." (PMID 22690216, 2012). "Previous studies have shown that early onset of puberty is associated with the emergence of several risk factors for CHD including hypertension, obesity, adverse blood lipid profile and high levels of insulin in adulthood." (PMID 22291964, 2012). "Further, obesity and colon cancer are frequently associated with systemic hormonal changes, particularly with high serum levels of insulin and leptin, two hormones that are thought to promote cancer initiation and progression." (PMID 23056418, 2012). "Low birth weight followed by catch-up growth and body fat accumulation during childhood is associated with increased risk of obesity, insulin and leptin resistance and CVD later in life." (PMID 22615820, 2012). "Autophagy is also important for organelle function and insulin signaling loss of autophagy is a critical component of defective insulin action in obesity." (PMID 23304112, 2012). "Obesity is associated with a whole variety of metabolic signals feeding back to the brain for example, leptin, insulin, or different cytokines." (PMID 22654904, 2012). "Obesity is often associated with increased serum glucose and triglycerides levels, as well as highly spiking insulin concentrations, which are risk factors for increasing the likelihood of tumour progression." (PMID 21179032, 2011). "Accordingly, mice deficient in RBP/RBP4 remained more insulin sensitive under conditions of diet-induced obesity." (PMID 22254074, 2011). "Such sudden accumulation of adipose tissue macrophages is a known feature of obesity, where it is linked with increased insulin resistance." (PMID 22018099, 2011).
Obesity (continued). "By using multivariate analysis, we found that factors significantly associated with obesity among women were diastolic blood pressure, insulin resistance, and employment status." (PMID 21159215, 2011). "This would offer an explanation for the epidemiological findings that obesity and decreased insulin sensitivity are risk factors of T1D." (PMID 22046124, 2011). "Some of these cells (possibly adipocytes themselves) produce insulin-desensitizing inflammatory molecules, and a number of researchers now believe that obesity is a low-grade inflammatory disease that causes diabetes." (PMID 21276254, 2011). "For example, subcutaneous and visceral fat differ in immune cell composition, insulin sensitivity, lipolysis, expression of glucose transporters, and obesity-associated adipocyte death and attendant inflammation." (PMID 22051061, 2011). "microRNAs (miRNAs) appear to play regulatory roles in many biological processes associated with obesity, including adipocyte differentiation, insulin action and fat metabolism." (PMID 21506921, 2011). "Treatment with the TACE-inhibitor Marimastat improved surrogate markers for insulin sensitivity and reversed steatosis in mouse models of diet-induced obesity and leptin deficiency, thereby attenuating post-operative injury following hepatectomy." (PMID 21980496, 2011). "Fasting insulin and cholesterol levels were independently associated with obesity in both CHC and HCC groups." (PMID 22044490, 2011). "One of the strategies the endocrine pancreas uses to adapt to changes in insulin resistant requirements associated with different physiological states, such as pregnancy, obesity, or ageing, is to expand the β-cell mass." (PMID 22208362, 2011). "Based on these findings, we propose that the mechanism of increased FGF21 levels in kidney disease is similar to those observed in obesity-associated resistance to insulin." (PMID 21525989, 2011). "It was also reported in this study that defects in oocyte developmental competence caused by obesity were reversed by treatment with insulin sensitisers before conception." (PMID 22203829, 2011). "A disruption in the condition of this organelle affects the fate of lipids, proteins, glucose and insulin and associates with common ailments including atherosclerosis, DM, obesity and neurodegenerative disease." (PMID 21568932, 2011). "Insulin resistant states such as obesity, metabolic syndrome, and DM2 cause impairment of downstream GLUT4 translocation by disruption of insulin receptor substrate-1 (IRS-1) associated PI3K signaling in the metabolic pathway of insulin." (PMID 21773024, 2011). "In summary, this study clearly shows that obesity in childhood carries a substantial inflammatory burden that is strongly, yet selectively, associated with specific functional alterations, such as insulin sensitivity or lipid homeostasis." (PMID 21274450, 2010). "There are theories involving an altered glucose-insulin metabolism in utero leading to an increased risk for obesity later in life." (PMID 21159203, 2010). "Over-expression of FSP27 promotes lipid storage, whereas FSP27 deficient mice have improved insulin sensitivity and are resistant to diet-induced obesity." (PMID 20649970, 2010). "In this experimental design, patients were otherwise healthy and matched for levels of obesity; thus, we expected to identify more subtle expression changes associated with insulin sensitivity status." (PMID 20361040, 2010). "Both TNF-α and JNK are implicated in inflammation-induced impairment of insulin signalling in obesity." (PMID 20508722, 2010). "Obesity-associated chronic inflammation is a key contributor to decreased insulin signaling throughout the disease progression, although the specific mechanisms that link inflammation to IR remain not fully understood." (PMID 20508742, 2010).
Obesity (continued). "In healthy subjects we identified clusters of proteins associated with BMI and insulin that included previously identified biomarkers for obesity-related disease risk and potential new biomarkers for which an association with disease is not well-established." (PMID 21203453, 2010). "Previously, we reported that adipocyte specific overexpression of PeriA caused resistance to diet-induced obesity and resulted in improved insulin sensitivity." (PMID 21103377, 2010). "Since obesity is often associated with alteration of glucose metabolism, we evaluated in vivo glucose tolerance and sensitivity to insulin of mice from the four experimental groups." (PMID 20376352, 2010). "Obesity in postmenopausal women has been associated with increased exposure to estrogen, insulin, and insulin-like growth factors (IGF) that are associated with breast carcinogenesis." (PMID 29147190, 2010). "Our work also presents nitrosative modification of insulin signaling proteins as a novel therapeutic target for improving muscle IR following LPS exposure during endotoxin shock or obesity-linked metabolic endotoxemia." (PMID 21206533, 2010). "This question is also relevant to obesity-linked inflammation since the finding that LPS levels are increased in obese insulin resistant mice as a result of perturbations of the gut microbiota that cause metabolic endotoxemia." (PMID 21206533, 2010). "There is also a disputed association of obesity-associated bone fragility with several IR-derived defects, such as high insulin levels, low insulin-like growth factor-1 synthesis, low serum adiponectin, and elevated levels of inflammatory cytokines." (PMID 20508742, 2010). "SNP rs27647 is situated in the promoter region of the gene and has been found associated with insulin level and obesity, while SNP rs35683 is situated in the first intron of the gene and has been found associated with BMI in a Caucasian population." (PMID 20920174, 2010). "Other reports from the DPP have highlighted the beneficial impact of lifestyle modification on other cardiovascular risk factors including glucose homeostasis, insulin sensitivity, lipid levels, inflammation, coagulation, and obesity." (PMID 19365563, 2009). "Left ventricular mass was then compared to serum and anthropometric markers of obesity linked to left ventricular mass, i.e. height, age, blood pressure, total fat mass, visceral fat mass, lean mass, serum leptin and fasting insulin level." (PMID 19393079, 2009). "Recent data have conclusively shown a causal relationship between obesity-induced overproduction of fat inflammatory mediators such as Ccl2, insulin resistance and steatogenesis." (PMID 19513120, 2009). "Diet-induced obesity has been associated with impaired insulin-stimulated glucose uptake in skeletal muscle and altered lipid metabolism in cardiac muscle." (PMID 19390571, 2009). "To determine how Mstn deletion causes reduced adiposity and resistance to obesity, we analyzed substrate utilization and insulin sensitivity in Mstn−/− mice fed a standard chow." (PMID 19295913, 2009). "Nevertheless, the cyclic AMP (cAMP) responsive element-binding protein-1 (CREB1) is expressed in the VMH, and CREB1−/− mice exhibit adult onset obesity associated with hyperphagia, elevated insulin and leptin levels, as well as leptin resistance." (PMID 19750222, 2009). "The association with obesity disappears when adjusting for age while that with insulin sensitivity association remains." (PMID 19390624, 2009). "In humans, obesity was shown to result in a significant elevation of LAR expression in skeletal muscle in association with considerably impaired insulin induced glucose disposal and enhanced phosphatase activity." (PMID 19356234, 2009). "Obesity in childhood is also associated with elevated blood pressure and adverse changes of CV risk factors, including changes in carbohydrate-insulin metabolism, especially in young white children." (PMID 19954521, 2009).
Obesity (continued). "Others have recognised that insulin levels per se cannot explain the disparity in the observed risk between obesity and premenopausal and postmenopausal breast cancer risk, whereas oestrogen concentrations are well correlated." (PMID 18665189, 2008). "It is therefore possible that impaired cerebrocortical insulin response at least partly accounts for the implication of FTO variants on obesity." (PMID 18799002, 2008). "We have previously shown that progressive obesity in aging LY mice is associated with a concomitant diminution in ovarian function, which is paralleled by acquired insulin and leptin resistance." (PMID 18348723, 2008). "Examinations of naturally occurring human polymorphisms have focussed on susceptibility toType II diabetes, insulin sensitivity, and obesity, and to date at least sevenpolymorphisms within the PPARG gene have been described." (PMID 18309368, 2008). "The comparable pattern of regulative proteins in the chronic environment of obesity and in acute inflammation suggests similar causative mechanisms of insulin resistance." (PMID 19087258, 2008). "Adiponectin acts principally as an insulin sensitiser; it is inversely associated with parameters of adult obesity and has anti-inflammatory and antiatherogenic effects." (PMID 16404369, 2006). "Obesity in pre-adolescent and adolescent girls is associated with higher basal insulin levels, which can impair oocyte maturation and stimulate androgen production in the ovary." (PMID 15987426, 2005). "FA with no rotation identified a factor (Factor 1) that was loaded mostly by central obesity, obesity risk factors and INS." (PMID 15656912, 2005). "While the smaller adipose cells tend to be more insulin sensitive, large adipocytes become insulin resistant and contribute more to the metabolic problems associated with obesity." (PMID 15530168, 2004). "Several investigators have found that there has been a positive association between insulin sensitivity and duration of obesity, i.e., those who are obese since childhood are more likely to remain insulin sensitive." (PMID 15530168, 2004). "Reported outcomes included improvements in insulin sensitivity, regulation of leptin levels, and modulation of the gut-brain axis, which may collectively contribute to a reduced risk of obesity." (PMID 41754191, 2026). "Notably, the reduction in the rate of non-obesity-related cancers over time was of a similar magnitude, with surgery associated with a 32% lower hazard (HRadj = 0.68) in the highest insulin third." (PMID 41490246, 2026). "In muscle, insulin-sensitive glucose disposal was restored, whereas obesity-associated adipose tissue changes largely persisted following CR, specifically the reduction in fasting lipolytic activity mediated at least, in part, by lower β-adrenergic receptor 3 expression." (PMID 42090498, 2026). "These processes contribute to the development and amplification of central insulin and leptin resistance, which may represent both predisposing factors for obesity and downstream consequences of chronic metabolic dysregulation." (PMID 41596611, 2026). "Further, insulin is adipogenic and thus contributes to obesity whereas metformin is associated with weight loss, making it difficult to interpret whether GLP-1 receptor agonist or the comparator medication is truly altering malignancy risk." (PMID 41583363, 2026). "Notably, bariatric surgery was also associated with a lower rate of non-obesity-related cancers in the subgroup with the highest insulin levels (HRadj = 0.68; 95% CI [0.47, 0.99]; p = 0.045)." (PMID 41490246, 2026). "In adipose tissue, SPMs counter obesity-associated TNF signaling that desensitizes insulin pathways in adipocytes: lipoxins restore IRS-1 phosphorylation and stimulate Akt activation, facilitating GLUT4 vesicular translocation and improving insulin responsiveness." (PMID 41516407, 2026).